TNF (tumor necrosis factor)
Diseases named in the same sentence as TNF in open-access papers (continued):
Sharing a sentence is not in itself a finding about the gene and the disease.
malaria (continued). "In an earlier work, a peak in HIV-1 MTCT was reported three months after the peaks of the rains in Cameroon, suggesting that the observed increase in HIV-1 MTCT could have been due to an increase of TNF-α in the placental environment as a result of malaria." (PMID 16796744, 2006). "The pyrogenic cytokine TNF-alpha is elevated in febrile malaria and may depress humoral immunity by impairing antigen handling by dendritic cells." (PMID 16271153, 2005). "Together, our data support the existence of a highly conserved TNF signaling pathway in mosquitoes that mediates cellular immunity and influences Plasmodium infection outcomes, offering potential new approaches to interfere with malaria transmission by targeting the mosquito host." (PMID 40608824, 2025). "Similarly, TNF-α levels were significantly higher in the malaria group." (PMID 40061813, 2025). "As a result, pregnant women with a history of malaria had high levels of all evaluated cytokines when compared to pregnant women without prior exposure to the parasite; this increase was more relevant among the cytokines IL-6, IL-8, IL-10 and TNF-α (respectively)." (PMID 39495782, 2024). "Other studies show that IL-6 acts in concert with TNF-α and other inflammatory mediators in the clearance of malaria parasites but a meta-analysis by Wilairatana, Mala showed that although IL-6 may be a marker of Plasmodium infection, increased levels are associated with hyperparasitaemia." (PMID 38404582, 2024). "For instance, the host cells elaborate IFN-γ, TNF-α, and IL-10 following exposure to malarial parasites and the increase in production of these cytokines contribute to the expression of the adhesion molecules often seen in patients with complicated and uncomplicated malaria." (PMID 39039450, 2024). "Furthermore, understanding factors that limit Tr1 induction—and promote CD4+ T cell production of TNFα—may help in the rational design of effective vaccines in malaria-endemic settings." (PMID 37634385, 2023). "The engaged immune cells release inflammatory factors, such as pro-inflammatory cytokines/chemokines (e.g. IL-1β, TNF-α, Il-12, IL-10, Il-6), nitric oxide (NO) and reactive oxygen species (ROS) that drive the inflammatory response and lead to the fever-like symptoms observed in malaria patients." (PMID 37350957, 2023). "While the importance of these TNFα expressing nnCD4+ T cells remains unclear, their presence in multigravid populations suggests a role in gravidity-dependent acquired immunity against malaria." (PMID 37634385, 2023). "Together, these data suggest that both the overall magnitude, and relative proportion, of malaria-specific nnCD4+ T cell responses differ across gravidity, with primigravid women tending to have a more IL-10 producing response, and multigravid women tending to have a more TNFα producing response." (PMID 37634385, 2023). "Co-infected mice exhibited decreased levels of pro-inflammatory cytokines (i.e. IFN-γ, TNF-α, and IL-12p70), in contrast to the level of anti-inflammatory cytokine IL-10, which was boosted in mouse serum, suggesting a protective function of IL-10 against complicated malaria." (PMID 37492527, 2023). "Although the proinflammatory cytokines, IL-12, IFN-γ, and TNF-α promote resistance and providing protection against Plasmodium infection, high levels of IFN-γ and TNF-α in serum have also been associated with severe anemia, cachexia and pathology of malaria disease." (PMID 36093199, 2022). "Besides, the results of KEGG pathway enrichment analysis showed that effects of hawthorn leaves on CHD may be due to its ability to target varied pathways simultaneously, such as pathways in cancer, TNF signaling pathway, malaria, and so on." (PMID 35783840, 2022).
malaria (continued). "Moreover, pathways such as NF-Kappa B signaling, RIG-I like receptor signaling, NOD like receptor signaling, Cytosolic DNA sensing, Influenza A, Malaria, TNF-signaling, Cytokine-cytokine receptor interaction and Toll like receptor signaling were significantly enriched during the SADS-CoV infection." (PMID 35697915, 2022). "However, elevated levels of proinflammatory cytokines such as TNF-α, IL-6, or IL-8 may be markers of severe malaria." (PMID 34790829, 2021). "Moreover, recent research states the role of TNF in lethal malaria forms." (PMID 34790829, 2021). "However, whether EBV and TNF-α together or independently form the driving force in Malaria disease severity (in Indonesia) remains to be studied further." (PMID 34962938, 2021). "We speculate that this balance of Ab-mediated activation may be beneficial, as excessive secretion of pro-inflammatory cytokines, such as IFNγ and TNFα, in the placenta of malaria-infected women, especially in primigravidae, has been associated with placental pathology and adverse clinical outcomes." (PMID 33602987, 2021). "However, when assessing TNF-α and Hb genotypes when compared with and without malaria there was no tight association, but there was an increasing trend in TNF-α levels in malaria positive groups." (PMID 33424841, 2020). "Also, it has been shown that the levels of TNF-α, IL-2, IL-10, IL-6 in Plasmodium-helminth co-infected individuals were significantly higher than the malaria-positive (MP) group dampening the immune response to malaria." (PMID 33170876, 2020). "Besides parasite detection and phagocytosis, monocytes are major producers of predominantly inflammatory cytokines in malaria, including TNF and IL‐12; these assist immune control of Plasmodium infection, but also contribute to the clinical symptoms of malaria." (PMID 32566226, 2020). "Hence, our results indicate that the deleterious role of caspase-8 in the hypersensitivity to septic shock in this malaria model may also involve the induction of TNFα expression." (PMID 32929083, 2020). "Increased levels of TH1-associated cytokines, such as TNF-α and IFN-γ, are observed in the blood and tissues in different clinical presentations of malaria, suggesting pivotal roles played by these cytokines in protection against malaria in both rodent and human malaria." (PMID 31867283, 2019). "Similarly, low levels of IL-1β and TNF-α have been found in patients with severe malaria." (PMID 30800644, 2019). "Since TNF-α appears to be important to some aspects of the pathogenesis in both SLE and P. falciparum malaria, we hypothesized a possible relationship between TNF-α promoter variants with predisposition to SLE, notably lupus nephritis, in patients residing in a malaria endemic area." (PMID 31409832, 2019). "It should be noted that some of these association signals could result from genotypic combinations with neighboring genes, namely lymphotoxin-alpha (LTA) and more detailed analysis of this region is needed to discern the involvement of TNF in human severe malaria." (PMID 31417551, 2019). "Finally, we proposed the essential mechanisms of protection for dexamethasone in experimental malaria, suggesting that PbA-iRBCs induce TNF release by endothelial cells and by Mφ, and then TNF upregulates EPCR expression in PMLECs, increasing iRBC adhesion through the EPCR pathway." (PMID 31871954, 2019). "Using a microchannel flow adhesion assay with TNF‐activated primary human microvascular endothelial cells, we demonstrate that IE isolated from Malawian paediatric CM cases showed increased binding to brain microvascular endothelial cells compared to IE from uncomplicated malaria (UM) cases." (PMID 30610112, 2019). "Endothelial responses to TNF, which was reduced in the brains of infected αD-/- mice, may be particularly important in differentially influencing vascular barrier integrity and other features of severe versus uncomplicated malaria phenotypes." (PMID 31869339, 2019).
malaria (continued). "Therefore, modulation of IL-10 production in malaria may be achieved by targeting the activities of upstream activating cytokines, such as IL-27, IL-21, type I IFNs, TNF, or TGFβ." (PMID 30809232, 2019). "Immunopathology of malaria disease involves proinflammatory cytokines such as tumor necrosis factor-alpha (TNF-alpha), Interleukin-12 (IL-12), and IFN-γ which may mitigate parasite development and stimulate monocyte phagocytosis towards clearance of parasitized red blood cells." (PMID 30154871, 2018). "Combined with TNF and CCL5 chemokine, they are proven to be crucial biomarkers in the profile of individuals with mild infection of P. vivax, and in contrast, there are positive correlations involving TNF and IFN-γ associated with pathogenicity in severe malaria." (PMID 30126413, 2018). "In murine models of virulent malaria infections, excessive IFN-γ or TNF production can lead to severe immunopathology suggesting that, although NK cells are beneficial during early immune responses to malaria, they may contribute to the detrimental effects of excessive systemic inflammation." (PMID 28337195, 2017). "However, it has been reported that hepatocyte dysfunction could occur as a result of accumulation of free heme and high levels of serum TNF-α during malaria." (PMID 28503569, 2017). "However, the frequency of CD4 cells producing IL10 but not inflammatory cytokines (IFNγ and TNFα) was associated with a decreased risk of clinical malaria once infected." (PMID 29097996, 2017). "Experiments in which IL-10 was administered in mouse models of malaria resulted in a lower production of TNF-α and a lower incidence of experimental cerebral malaria (ECM), leading some to hypothesize that IL-10 counteracts the potentially pathological host proinflammatory response to malaria." (PMID 28122790, 2017). "A population of monofunctional CD8+ T cells, positive for IFNγ, but not for IL-2 or TNFα, previously found associated with delay to patency following controlled human malaria infection of malaria-naïve adult volunteers using this vaccine was detected in all three infant groups." (PMID 29213269, 2017). "In contrast, reduced TNF-α levels in the coinfected children relative to the malaria monoinfected children may be related to counterregulatory activities of IFN-induced increased NO that downregulate nitric oxide synthase- (NOS-) inducing cytokines, such as TNF-α, through a feedback mechanism." (PMID 27418744, 2016). "An in vitro study found that BAT1 appeared to decrease the expression of TNF and IL-6; thus the G allele of DDX39B-22C > G, which enhances the expression of BAT1, may be protective against complicated malaria by decreasing the expression of proinflammatory cytokines." (PMID 25038626, 2014). "Previous studies showed overexpression of pro-inflammatory cytokines TNFα, IL-1α and IL-6 in CM patients promotes pathogenesis of CM (acute immune activation, promotion of adhesion molecules, leukocyte recruitment, fever and BBB disruption) and were associated with severe and lethal malaria." (PMID 24433482, 2014). "Similarly, higher TNF-α was seen in cerebral malaria compared to uncomplicated malaria." (PMID 24669217, 2014). "Importantly, we demonstrate for the first time that CD14+CD16+ monocytes in malaria patients exhibited greater phagocytic activity and produced higher levels of intracellular TNF-α and reactive oxygen species, indicating their important role in parasite control and host resistance to infection." (PMID 25233271, 2014). "However, in the 96 h supernatant culture, the dynamics of cytokine responses differed from those depicted on plasma assays; in presence of PvMSP-119 stimulus, higher levels of TNF were noted in supernatant 96 h culture of malaria patient’s cells while low levels of IFN-γ and IL-10 were verified." (PMID 24041406, 2013).
malaria (continued). "It has been also shown that cytokines play an important role in the immunopathology of malaria and many field studies have described an association of specific cytokines with severity of disease, in particular IL-2, IL-12, IFN-γ, IL-1β, IL-6, TNF, IL-4, IL-10, MIP-1β, and TGF-β." (PMID 22280502, 2012). "The presence of severe malaria has been strongly attributed to an exaggerated immune response of the host towards parasite antigens and several authors reported on the positive correlation between high TNF production and cerebral malaria in humans as well as in animal models." (PMID 22316273, 2012). "With regard to malaria, the immune mechanisms are not fully understood yet, but it is known that the cytokine profile, which is proven effective in tackling the infection, is the mechanism that involves cellular response by helper T lymphocytes (Th) 1, with prevalence of TNF-α, IFN and IL-12." (PMID 23208374, 2012). "If TNFα producing CD4+ T cells are causally related to protection, they should be associated with protection whether they are acquired by vaccination or by natural exposure to malaria parasites." (PMID 21998698, 2011). "In addition, when data were combined for all ethnic groups, lack of association between any pattern of TNF allele polymorphism as well as each individual single SNP and malaria disease pathogenicity/severity was found." (PMID 20846452, 2010). "Although TNF may protect against the parasites, local superproduction leads to tissue damage; in addition, elevated levels in the blood are related to sickness and death in cases of severe malaria." (PMID 18816374, 2008). "However, despite recent reaffirmation of the GPI/cytokine/disease concept, the group that first suggested that GPI was the main TNF inducer in malaria appear to have recently changed their disease model to one that eliminates a requirement for inflammatory cytokines." (PMID 17029647, 2006). "Indeed, the notion of the vomiting and nausea of severe malaria being best explained by intestinal vacular sequestration is still put forward, many years after TNF, the major cytokine increased in the circulation in severe malaria, was shown to produce these changes when injected into volunteers." (PMID 17029647, 2006). "Cord haemoglobin levels were examined in 32 malaria-infected and 58 uninfected women in Blantyre, Malawi, in relation to maternal haemoglobin levels, malaria status, and markers of foetal haematological status, hypoxia, and inflammation, including TNF-α, TGF-β, and ferritin." (PMID 16122391, 2005). "In humans, malaria during pregnancy results in elevated levels of numerous cytokines, including IFN-γ, TNF-α, IL-4, IL-6, IL-10, and CXCL9 in peripheral circulation, with some of these cytokines linked to increased risk of pregnancy loss." (PMID 40470930, 2025). "It has been documented that the blood-stage cycle of the malaria parasite is characterized by an upregulation of inflammatory cytokines like IL-6, IFN-γ, and TNF-α, which play a pivotal role in controlling the growth of the parasite and its elimination." (PMID 40014608, 2025). "The findings highlight the potential of IL-6, TNF-α, and APOA1 as biomarkers and therapeutic targets in malaria." (PMID 40061813, 2025). "The median TNF-α level for all participants was 78.2 pg/mL (IQR: 65.6 – 99.1), with those in the malaria group having a median of 90.8 pg/mL (IQR: 75.4 – 107.5), compared to 48.0 pg/mL (IQR: 35.0 – 78.0) in the control group (p < 0.001)." (PMID 40061813, 2025). "Malaria-infected hosts mount pro-inflammatory Th1 immune response – dominated by cytokines like interferon-γ (IFN-γ) and tumor necrosis factor-alpha (TNF-α) – to clear Plasmodium parasites." (PMID 40460079, 2025). "Tumor necrosis factor-alpha (TNF-α) and interleukin-6 (IL-6) are important in the pathogenesis of malaria-induced lung pathology." (PMID 40917784, 2025).
malaria (continued). "For example, IL-1β can synergize with IL-1α and TNF-α to enhance nitric oxide (NO) and IFN-γ production in murine malaria models." (PMID 40980010, 2025). "On admission, the concentrations of IL-1β (p = 0.0026), IL-2 (p < 0.0001), IL-6 (p = 0.0009), TNF-α (p > 0.0001), and IFN-γ (p > 0.0001) were significantly upregulated in patients with malaria and typhoid comorbidity, comparing to healthy controls." (PMID 40014608, 2025). "A type 1 immune response is strongly induced in C57BL/6 mice during malaria and leishmaniasis, resulting in the production of pro-inflammatory cytokines such as IFN-γ and TNF." (PMID 40720541, 2025). "The pathophysiological mechanism of pain and other symptoms can involve the release of inflammatory cytokines, especially TNF-α, IL-1, IL-6, IFN-γ, IL-8, IL-10, and IL-13, during the inflammatory response induced by malaria." (PMID 38774541, 2024). "In acute phase of malaria infection pro-inflammatory cytokines such as TNF-α and IFN-γ are produced to eliminate the malaria parasites." (PMID 39039450, 2024). "In the present study, children with severe malarial anemia had significantly elevated plasma levels of TNF‐α, IFN‐ɣ, IL‐1β, IL‐6, GM‐CSF and IL‐10 than those with uncomplicated malaria, and this is in consonance with earlier findings." (PMID 39240033, 2024). "Participants with malaria had higher TNF‐α/IL‐10, TNF‐α/TGF‐β, IFN‐ɣ/TGF‐β, IL‐1β/TGF‐β and, but lower IFN‐ɣ/IL‐10, IL‐1β/IL‐10, and IL‐6/TGF‐β ratios than those in the control group." (PMID 39240033, 2024). "Children with severe malarial anemia had higher plasma levels of TNF‐α (p < .001), IFN‐ɣ (p < .001), IL‐1β (p < .001), IL‐6 (p < .001), GM‐CSF (p < .001), and IL‐10 (p < .001) than those with malaria only, and mild/moderate anemia." (PMID 39240033, 2024). "In the current study, participants with malaria had higher TNF‐α/IL‐10, TNF‐α/TGF‐β, IFN‐ɣ/TGF‐β, and IL‐1β/TGF‐β, but lower IFN‐ɣ/IL‐10, IL‐1β/IL‐10, and IL‐6/TGF‐β ratios than those in the control group." (PMID 39240033, 2024). "Severe malaria patients have been found to produce high levels of systemic proinflammatory cytokines such as IFN-γ, IL-1β, IL-6, and TNF-α." (PMID 38787228, 2024). "Elevated levels of pro-inflammatory cytokines such as TNF-α, IL-1β, and IFN-γ are typically observed in uncomplicated malaria." (PMID 38694310, 2024). "IFN-γ, IL-2, IL-5, IL-6, and IL-12 were increased in mild malaria, whereas TGF-β, TNF, IL-10, and IL-1β were particularly elevated in cerebral malaria." (PMID 38774541, 2024). "First, we mimicked the inflammatory environment of severe malaria, and set up a 24-h murine model of ALI using iRBCs combined with TNF-α." (PMID 38286811, 2024). "TNF levels were significantly increased in asymptomatic malaria and HBV coinfections, but their levels were significantly decreased in uncomplicated malaria and HBV coinfections." (PMID 36716305, 2023). "For intestinal parasite infections, increased TNF, IL-1, IL-6, IL-10, CCL2 and decreased IL-4, IL-17, TGF-β were observed in malaria coinfections compared to intestinal parasite monoinfection." (PMID 36716305, 2023). "As presented above, TNF-α, CSF-2, and CXCL8 have been shown to be at increased levels during both malaria and babesiosis." (PMID 36839438, 2023). "Tumor necrosis factor-alpha (TNF-α) is predominantly produced by γδ T cells and CD14+monocytes during immune responses to malaria and helps in the control ofparasitemia." (PMID 38774844, 2023). "Distinct cytokine profiles in malaria and HBV coinfections were TNF, IFN-γ, IL-4, IL-6, IL-10, IL-12, and CCL2." (PMID 36716305, 2023). "While a significant decrease in TNF levels was found in uncomplicated malaria and HBV coinfections, TNF levels were increased in asymptomatic malaria and HBV coinfections compared to malaria monoinfections." (PMID 36716305, 2023).